WT1 (WT1 transcription factor)
Diseases named in the same sentence as WT1 in open-access papers (continued):
Sharing a sentence is not in itself a finding about the gene and the disease.
tumor (continued). "Wilms' tumor gene (wt1) consists of 10 exons that encode a zinc finger transcription factor involved in genitourinary development during embryogenesis." (PMID 34845427, 2021). "One possibility is that CMIP sequence is mutated in tumor cells—like tumor suppressors such as WT1 in some malignancies-." (PMID 33917766, 2021). "Vaccination of AML patients with immunogenic tumor-associated antigens such as Wilms tumor antigen-1 (WT1) and NY-ESO have also demonstrated a survival benefit for patients with an immune response." (PMID 33718228, 2021). "All three had a confirmed predisposition, i.e., a germline WT1-mutation (n = 2) and hypermethylation of the H19-locus in healthy kidney and tumor tissue only (n = 1)." (PMID 34884260, 2021). "A BiTE targeting Wilms’ tumor protein (WT1) led to the expansion of secondary T cell clones (with specificity for tumor-associated antigens other than WT1) in in vitro co-cultures of patient PBMCs with autologous tumor cells." (PMID 33939108, 2021). "MDSCs have been reported to transcriptionally control the expression of CD31 and CD117 through the frequent expression of the Wilms’ tumor suppressor Wt1, and knockout of Wt1 in MDSCs is sufficient to cause regression of tumor vascularization." (PMID 35003065, 2021). "The Wilms tumor 1 (WT1) protein is an immunogenic tumor-associated antigen that is over-expressed in CD34 + MDS stem cells and AML blasts which elicits T-cell mediated myelosuppression and is a candidate antigen for vaccine therapy." (PMID 34638510, 2021). "Tumor response to preoperative chemotherapy varies significantly between the different syndromes and depends on the presence of a stromal subtype or WT1 mutation." (PMID 34638500, 2021). "The Wilms tumor suppressor gene Wt1 encodes a zinc finger transcription factor, which is highly conserved among vertebrates." (PMID 35087838, 2021). "The transcription factor Wilms' tumor 1 (WT1) is one of the best characterised and most highly immunogenic tumor‐associated antigens (TAAs) and is an excellent target for therapeutic cancer vaccines." (PMID 32547743, 2020). "Among them, a randomized phase II study for the Wilms’ tumor gene 1 (WT1) vaccine showed promising results; WT1, which is ranked as the top antigen among 75 tumor-associated antigens (TAAs), is one of the most promising TAAs." (PMID 31997007, 2020). "Lastly, the WT1 gene encodes a transcription factor that can act as both a tumor suppressor—inducing kidney tumors when mutated—and an oncogene that is highly expressed in many tumor types." (PMID 32605217, 2020). "ErbB2 and WT1 are not only tumor associated antigens for immunological targeting but also biomarkers of cancer cell proliferation and survival, especially GBM." (PMID 32733437, 2020). "Ten years ago, we described five cell lines with WT1 mutations and more recently we reported cell lines from a tumor and metastasis of the same patient; the tumor cell line was immortalized with ts SV40 largeT antigen (LT) and Telomerase." (PMID 33379206, 2020). "WT1 is an excellent tumor-associated antigen to target for immunotherapy and WT1 vaccine-based clinical trials have proved safety and efficacy." (PMID 32856872, 2020). "Autologous moDCs transfected with messenger RNA (mRNA) encoding for WT1 and autologous moDCs loaded with autologous/allogeneic tumor lysate." (PMID 32582537, 2020). "The presence of only mutant WT1 alleles in all cell cultures confirms their tumor origin and the homogeneity of the cultures." (PMID 33379206, 2020). "The decrease of antitumor T-cell response in the metastatic stage was also found with two additional shared tumour-associated antigens such as WT-1 and NY-ESO-1." (PMID 31358938, 2019). "Several of these proteins have tumor suppressor function in human and other animals, namely Wilms Tumor 1 Associated Protein (WT1), Heat Shock Protein 90 (HSP90), Glioma Pathogenesis-Related Protein 1 (GLIPR1) and Matrix Metalloproteinase B (Smed-MMPB)." (PMID 29967069, 2018).
tumor (continued). "The association between reduced WT1 in tumour-free tissue and poor prognosis suggests a protective role for WT1 in the healthy breast." (PMID 30374123, 2018). "The Wilms tumor 1 gene (WT1) encodes a zinc finger transcriptional regulator that acts as a tumor suppressor in various cell types, with target genes implicated in cell differentiation, apoptosis and cell cycle regulation." (PMID 30450160, 2018). "Wilms tumor 1 (WT1) is a zinc finger transcriptional regulator, and has been implicated as both a tumor suppressor and oncogene in various malignancies." (PMID 30450160, 2018). "Patient Wilms12 had a germ line heterozygous WT1 mutation, and the primary tumor sample was homozygous for this mutation." (PMID 29542868, 2018). "Increasing WT1 levels are commensurate with increasing tumor grade and associated with poor patient prognosis." (PMID 29623275, 2018). "Tumours with WT1 mutations mimic the entire kidney development with divergent mesenchymal differentiation." (PMID 29040332, 2017). "Although the evidence for CTNNB1 mutation being a late event is inconsistent, these studies, and others (Refs 34, 35) clearly demonstrate that WT1 mutation can follow the 2-hit tumour suppressor model for the development of cancer." (PMID 28716159, 2017). "Of 10 tumours with WT1 mutations, WT1 protein was detectable in two tumours both of which had constitutional missense WT1 mutations." (PMID 29040332, 2017). "Latter on, cytogenetic and molecular studies of tumor material from WT sporadic cases showed the presence of somatic inactivating mutations or deletions of WT1 in up to 15 % of the cases." (PMID 26913079, 2016). "The presence of different CTNNB1 mutations supports the sequential linear model whereby initiating mutations first occur in WT1, and for tumor development, additional CTNNB1 mutations are needed." (PMID 27213811, 2016). "The Wilms’ tumor transcriptional regulator WT1 can exhibit both oncogenic and tumor suppressor activities depending on its association with specific co-regulators." (PMID 27144453, 2016). "Four MLLT1-mutant tumours arose in kidneys with multiple ILNRs, a feature thus far predominantly recognized in patients with syndromes associated with germline WT1 mutations." (PMID 26635203, 2015). "Sufficient DNA was available on 16/19 MLLT1-mutant tumours to perform mutation analysis for WT1, CTNNB1, WTX, DROSHA, DGCR8, and SIX1/2 and this revealed five CTNNB1 mutations, one WTX mutation, and no WT1 DROSHA, DGCR8, or SIX1/2 mutations." (PMID 26635203, 2015). "This fusion product causes a loss of the tumor suppressor function of WT1 and a putative upregulation of various families of growth factors from the EWS gene." (PMID 24987737, 2014). "The Wilms' tumor transcription factor (WT1) was originally classified as a tumor suppressor, but it is now known to also be associated with cancer progression and poor prognosis in several malignancies." (PMID 25025131, 2014). "In fact, it was originally recognized as a tumor suppressor gene because of WT1 mutations were found to cause urogenital diseases and kidney tumors but, in several cases, evidence would suggest an oncogenic role." (PMID 25474318, 2014). "The recent prioritization of tumor-associated peptides ranked WT1 as the top target due to its immunogenicity, restricted expression in normal tissues, and a strong correlation with tumorigenesis." (PMID 23970885, 2013). "While we have observed functional changes with over-expression of both isoforms of EWS/WT1 in MEFs, much work remains to be completed in order to understand how these splice variants contribute to tumor formation." (PMID 24321497, 2013). "WT1 was associated with tumor grade (P = 0.025) and RSPO1 was associated with progesterone receptor expression (P = 0.019)." (PMID 24373193, 2013). "WT1 was first identified as a tumor suppressor based on its mutational inactivation in Wilms’ tumors of the kidney." (PMID 23298185, 2013).
tumor (continued). "Six different SNPs in WT1 were identified and we demonstrated at least one or two copies of the minor allele in 61% of ccRCC tumour samples." (PMID 23484026, 2013). "Conversely, mutation of the WT1 tumour suppressor gene results in ASF/SF2 hyperphosphorylation and expression of pro-angiogenic VEGF-A isoforms." (PMID 23851566, 2013). "Characteristics of Wilms’ tumour gene 1 (WT1) single nucleotide polymorphism (SNP) in ccRCC tumour and corresponding tumour-free renal cortical tissues." (PMID 23484026, 2013). "In tumors from individuals with constitutional WT1 mutation, the wild-type WT1 allele was somatically inactivated in the tumor, either by UPD or by a somatic mutation." (PMID 22470196, 2012). "Another more commonly recognized example is Wilm's tumor gene, WT1, which encodes up to 24 different isoforms which have distinct but also overlapping cellular and developmental functions." (PMID 21490919, 2011). "Alterations in the pattern and efficiency of alternative splicing of several pre-mRNAs (e.g. CD44, BRCA1, WT-1) have been implicated in tumourigenesis and correlated with tumour progression." (PMID 18949081, 2008). "Alterations in the pattern and efficiency of alternative splicing of several pre-mRNAs (e.g. CD44, BRCA1, WT-1) have been implicated in tumorigenesis and correlate with tumour progression." (PMID 12087473, 2002). "WT1′s tumor suppressor activity may be compromised by loss-of-function mutations, which would promote unchecked growth." (PMID 41155227, 2025). "Targeted sequencing confirmed the tumor origin of all cell types via shared WT1 mutations." (PMID 41002429, 2025). "Additionally, as WT1 is an important regulator of tumor growth, safety concerns associated with a generalized overexpression must be considered." (PMID 39768169, 2024). "The National Cancer Institute Cancer Panel recently identified WT1 as a major tumor-associated antigen that could be targeted." (PMID 38280040, 2024). "As a tumor‐associated antigen, high levels of WT1 protein expression can induce an immune response." (PMID 38742454, 2024). "Moreover, recent results have been shown a Wilms’ tumour 1 (WT1) IHC expression on tumor cells, underlining the value of WT1 peptide as an immunotherapy target, particularly WT1 peptide vaccination as a new avenue for treatment of advanced or recurrent TETs." (PMID 38966177, 2024). "Wilms’ tumor 1 (WT1) is a promising tumor-associated antigen for cancer immunotherapy." (PMID 35699757, 2023). "Importantly, higher WT1 levels were obviously associated with advanced T/N stage and tumour grade (P < 0.05)." (PMID 37667197, 2023). "Wilms’ tumor protein 1 (WT1) is a tumor-associated antigen overexpressed in various cancers." (PMID 36853720, 2023). "Wilms tumor 1 (WT1) overexpression on tumor cells is linked to a poor prognosis in AML patients." (PMID 36261831, 2022). "Distinct tumor susceptibilities of WT1 and WT2 mice could be explained by their differences in gut microbiota composition." (PMID 36726985, 2022). "The mutated variant showed a weaker effect in inhibiting tumor cells than wild‐type WT1." (PMID 33942367, 2021). "Finally, we evaluated two CD169-targeting nanovaccine platforms, antibody-based and liposome-based, and we showed that CD169+ monocytes efficiently presented tumor-associated peptides gp100 and WT1 to antigen-specific CD8+ T cells." (PMID 34394090, 2021). "Additionally, WT1 as a tumor-associated antigen stimulates the growth of WT1-specific CD8+ cytotoxic T cells which is associated with better BC outcomes." (PMID 33987034, 2021).
tumor (continued). "To determine whether the tumor-associated antigens that were used for the synthesis of the branched multipeptide were indeed present on GL261 cells, we estimated the expression of the two tumor-associated antigens (ErbB2 and WT1) on GL261 cells." (PMID 32733437, 2020). "The mutation in WT1 is present in blood DNA and is homozygous in the tumor." (PMID 33379206, 2020). "The higher expressions of USP5 and WT1 are associated with tumour metastasis." (PMID 31845546, 2020). "The expression of WT1 was associated with tumour metastasis." (PMID 31845546, 2020). "Cells with a heterozygous WT1 mutation (first hit) that also harbor a CTNNB1 mutation could not be identified in our cell culture conditions but they may exist in the tumor in vivo." (PMID 33379206, 2020). "Tumor-associated antigens (TAAs) such as the Wilms tumor gene WT1 have the potential to generate tumor antigen-specific T cells which promote a GvL effect and display selective cytotoxicity to leukemic cells while avoiding side effects of allogeneic HSCT like graft versus host disease (GvHD)." (PMID 30678050, 2019). "The Wilms Tumor 1 (WT1) is a one of the most promising tumor associated antigens." (PMID 30542516, 2018). "Whilst WT1 over-expression and null mutations have both been documented in cancer, implicating its dual properties as a proto-oncogene and tumor suppressor, recent evidence has begun to demystify potential epigenetic regulatory functions of this protein in malignant neoplasms." (PMID 29623275, 2018). "Immunohistochemistry for the tumour markers Pax8 and WT1, commonly associated with EOC and HGSOC18, was performed to determine the tumour cell load in tissues and demonstrated the presence of micro-metastasis of tumour cells in some of the macroscopically non-cancerous tissues measured." (PMID 30279418, 2018). "All seven tumours carrying constitutional WT1 mutations had the protein-expression characteristics of UB-derived structures, supporting the hypothesis that stem cells with the initiating mutations develop into both tumorigenic MM and UB cells." (PMID 29040332, 2017). "Of ten tumours with WT1 mutations, nine had a stromal-predominant histology." (PMID 29040332, 2017). "Furthermore as the tumor and the cell line have the same WT1 alteration but different CTNNB1 mutations this supports the model that the WT1 alteration occurs first, with a high selection pressure to acquire mutations in CTNNB1." (PMID 27213811, 2016). "Disruption of WT1 function has been implicated in the formation of many different tumor types." (PMID 27275197, 2015). "These four immunohistochemical markers—SF-1 (steroidogenic factor-1), inhibin-α, WT1 (Wilms tumor protein 1), and calretinin—provide critical diagnostic information for ovarian tumor classification and represent a powerful panel for distinguishing between different tumor types." (PMID 41373846, 2025). "Similarly, WT1, frequently mutated in WT, interacts with the histone methylation machinery and influences H3K4me3; loss of WT1 function reduces this activation landscape at key differentiation genes, blocking nephron maturation and promoting tumor growth." (PMID 40722750, 2025).
tumor (continued). "Among the patients analyzed, we hypothesized that harboring low-level WT1 expression may be a hallmark of complex disease, with mutations in key myeloid tumor suppressor genes accumulating over time, signifying a significant correlation between low WT1 expression and adverse genomic profiles." (PMID 40227798, 2025). "Additionally, HMA application after transplantation can reactivate tumor suppressor genes and re-expression HLA-DR in tumor cells, and is associated with an increase in the proportion of WT1 positive cytotoxic T lymphocytes (WT1+CTL)." (PMID 37435080, 2023). "However, Wt1 upregulation to enhance cardiac repair might promote tumor growth in patients at risk and should be cautiously monitored." (PMID 34299295, 2021). "Furthermore, WT1 haploinsufficiency may promote the accumulation of somatic mutations or mutations of other epigenetic factors in progenitor cells, leading to tumor transformation." (PMID 32766158, 2020). "Indeed WT1 mutations could be detected in both the epithelial as well as the stromal cells, thereby confirming that the stromal cells are indeed tumour cells." (PMID 32161258, 2020). "Furthermore, WT1-BiTE therapy induced long-term T-cell responses against tumor-associated epitopes other than WT1 because of epitope spreading, which could greatly enhance the therapeutic efficacy of this bispecific construct." (PMID 28157217, 2017). "Thus we cannot exclude the possibility that mutations in other tumor suppressor pathways could also co-operate to drive EWS/WT1 oncogenic function." (PMID 24321497, 2013). "The tumor data from individuals with constitutional defects strongly supports this sequence as eight of nine tumors from individuals with constitutional WT1 mutations had somatic pUPD 11p15, whereas none of 11 individuals with constitutional 11p15 defects had somatic WT1 mutations." (PMID 22470196, 2012). "In clinical cohorts, WT1 was significantly downregulated in tumor tissues compared to normal prostate; however, preserved high WT1 expression correlated with improved disease-free survival." (PMID 41868121, 2026). "INI-1 was retained in the tumor cells, and WT1, desmin, myogenin, BCOR, TLE-1, CD45CLA, and synaptophysin were all negative (not shown)." (PMID 41230381, 2026). "Given its multifaceted role in hematopoiesis, leukemogenesis, and tumor progression, WT1 represents a promising candidate for biomarker discovery and therapeutic targeting in AML." (PMID 40507300, 2025). "After two weeks of treatment, WT1 silencing showed strong anti-tumor effects, leading to a reduction in tumor mass and significantly delaying animal death." (PMID 40724842, 2025). "After the development of the tumor, the formulations containing WT1 peptide, R848, OVA peptide, or WT1 long peptide were individually applied to the abdominal skin for 24 h and removed the following day." (PMID 40333258, 2025). "Western blot analysis of tumor lysates from M02 was positive for WT1 expression, while M10 showed Pax8 and WT1 positivity, consistent with immunohistochemistry analysis from both patients’ original specimen." (PMID 41413213, 2025). "Tumor cells are generally diffusely positive for WT-1 and often locally positive for cytokeratin (CK), EMA, CD10, and calretinin." (PMID 41244785, 2025). "NR5A1 regulates other target genes, such as SRY, responsible for testicular differentiation, WT1, and DHH, associated with gonadal abnormalities and increased risk of tumor." (PMID 41303802, 2025). "Additional candidate EC GWAS susceptibility genes encoded upstream regulators, such as WT1, whose regulatory effects in Ishikawa cells (0.1 μM GZD824) were linked to the migration of tumour cell lines." (PMID 39739675, 2025). "We thereby identified 15 children with a WT1 and 6 children with a TRIM28 germline mutation, interrogating their tumours by whole genome or exome sequencing, methylation arrays and RNA sequencing." (PMID 39665570, 2025).